YY1 (YY1 transcription factor)
Diseases named in the same sentence as YY1 in open-access papers (continued):
Sharing a sentence is not in itself a finding about the gene and the disease.
tumor (continued). "Our TF enrichment results in tumor cells are consistent with many previous studies which demonstrated that TF of YY1 could drive many aggressive cancer phenotypes." (PMID 36077333, 2022). "However, our findings suggested that increased YY1 expression expedited tumor cell EMT and aggressive growth in high‐grade BCa by transactivating the KTN1 gene." (PMID 35811688, 2022). "Recent studies have shown that lncRNAs can regulate YY1 network to control tumor growth." (PMID 36626426, 2022). "Although we have described the mechanisms related to YY1 and lncRNA network in recent years, the mechanisms still need to be further discussed before we can have a comprehensive and clear understanding of malignant tumor transformation." (PMID 36626426, 2022). "In addition, YY1 regulates several hallmarks of cancers, including deregulated cell proliferation, metabolic reprogramming, tumor angiogenesis, cancer cell metastasis and evasion from immune surveillance." (PMID 35406384, 2022). "However, YY1 is also reported to play a tumor suppressor role, particularly in the case of pancreatic cancer." (PMID 35383155, 2022). "Tumor cases were separated into high-expression and low-expression groups based on YY1 expression levels, and then, the TCGA and GEO datasets were utilized to investigate the link among YY1 expression and the prognosis of patients with various malignancies." (PMID 35791393, 2022). "Moreover, YY1 plays an essential role in carcinogenesis, as it controls the expression of various oncogenes and tumor suppressors, and regulates cell cycle, proliferation, differentiation, and apoptosis." (PMID 35408813, 2022). "Due to the small number of tumor samples with YY1 gene mutation in the database, all data had no statistical significance." (PMID 35791393, 2022). "Therefore, YY1 directs the apoptosis-anti-apoptosis balance in favor of tumor cells survival, protecting the cells from damage and activating autophagy-mediated survival." (PMID 35719931, 2022). "Upon stratification of the samples based on tumor grade, YY1 was found significantly upregulated in higher grade samples (Grades 3 and 4, G3–4) compared to lower grade ones (Grades 1 and 2, G1–2), whereas RKIP was significantly downregulated (p = 0.0013 and p = 0.0207, respectively)." (PMID 35205667, 2022). "Recent studies have shown that YY1 is also involved in tumor metabolic reediting." (PMID 35359580, 2022). "In tumor cells, YY1 plays a role in tumor angiogenesis by promoting hypoxia inducible factor 1 (HIF1)-dependent expression and vascular endothelial growth factor (VEGF) production, whereas the function of endothelium-specific YY1 in vascular development and angiogenesis is still unclear." (PMID 35791393, 2022). "Corresponding rescue experiments also demonstrated that the treatment of YY1 knockdown could reverse the original tumor-promoting effect produced by circPTPRF overexpression." (PMID 36397164, 2022). "The activation or inactivation of YY1 transcription factor will lead to uncontrolled expression of multiple gene sets, thus promoting cancer development, cell survival, and proliferation and inducing tumor angiogenesis." (PMID 35359580, 2022). "Moreover, according to previous studies, knockdown of YY1 can significantly block the tumor malignance and reverse the resistance." (PMID 36059990, 2022). "Various studies had also shown that YY1 could regulate the expression of immune cells and participate in tumor cell immune escape." (PMID 35359580, 2022). "YY1 is an attractive drug target due to its central role in tumor progression." (PMID 36059990, 2022). "In particular, various reports demonstrated that MYH9 is involved in tumor proliferation, migration, and metastasis, in this study, YY1 and MYH9 may be the upstream and downstream molecule of FGL1, respectively." (PMID 36268014, 2022). "We therefore hypothesized that HIF-1α is involved in positively regulating YY1 and is the reason for chemoresistance in tumor cells." (PMID 35163649, 2022).
tumor (continued). "The transcription factor Yin-Yang-1 (YY1) is known to play a fundamental role both in normal biological processes such as embryogenesis, differentiation, replication, cell proliferation, and in mechanisms of carcinogenesis, tumor progression and metastasis." (PMID 35163649, 2022). "Importantly, within the other non-tumor cells (stromal, myeloid, B and T cells) only YY1 was expressed, while BCL2L15 was sparsely detected." (PMID 34445183, 2021). "Overexpressing YY1 reversed the tumor-suppressive effect mediated by MIR31HG knockdown." (PMID 34485123, 2021). "Besides, our current study verified the regulatory mechanism between miR-34a and YY1 expression in repressing NSCLC tumor growth and metastasis." (PMID 33796457, 2021). "YY1 inhibits reactive oxygen species and promotes tumor cell death to suppress the immune system." (PMID 33985581, 2021). "Finally, this group found that YY1 acts as a tumor suppressor by downregulating MMP10 expression through the Muc4/ErbB2/p38/MEF2C axis." (PMID 33985581, 2021). "Interestingly, ectopic YY1 expression rescued the inhibition of tumor growth in vivo and in vitro induced by downregulation of linc00668." (PMID 33728560, 2021). "Therefore, we concluded that YY1 promoted trophoblast invasion to endothelial cells, which was also consistent with many studies on tumour diseases." (PMID 33942988, 2021). "Combination therapy with a YY1 inhibitor may enhance the sensitivity of tumor cells to immunotherapeutic drugs." (PMID 33985581, 2021). "Subsequently, we focused on the level of YY1 in xenograft tumours." (PMID 33675150, 2021). "Evidence supporting this hypothesis includes YY1 overexpression in tumor samples of the patients and inhibition of in vitro and in vivo tumorigenic potential by YY1 downregulation." (PMID 33728560, 2021). "In addition, YY1 can inhibit autophagy in tumor cells via miRNAs, enhancing the sensitivity to chemotherapeutic drugs." (PMID 33985581, 2021). "However, after a PDAC tumor is formed, YY1 begins acting as a tumor suppressor, inhibiting its own high expression." (PMID 33985581, 2021). "YY1 is a zinc finger transcription factor widely expressed in various tissues and participates in various biological processes such as embryonic development and differentiation, tumor metastasis, and cell proliferation." (PMID 33996974, 2021). "Collectively, our results demonstrate that endothelial YY1 has a crucial role in tumor angiogenesis and suggest that targeting endothelial YY1 could be a potential therapeutic strategy for cancer treatment." (PMID 33235311, 2020). "The O-GlcNAcylation of RACK1 may therefore modulate the melatonergic pathway in the tumour microenvironment via both YY1 and NLRP3." (PMID 33375613, 2020). "Additionally, YY1 in vitro can promote the transformation of B lymphocytes and contribute to tumor progression, or contribute to the chemoresistance of NHL." (PMID 33194748, 2020). "Nevertheless, it remains unknown whether YY1 in ECs contributes to tumor angiogenesis and tumor growth." (PMID 33235311, 2020).
tumor (continued). "Moreover, when samples were divided into six subgroups according to the tumor type, BL patients showed a significantly higher expression of both YY1 and BIRC5, if compared with less aggressive B-NHLs (including FL, MCL and MZL)." (PMID 32899428, 2020). "Relevantly, the components of the biological axis E2F/ITAG6/YY1 were significantly up-modulated in TNBC tumors in comparison with other tumor types, corroborating our hypothesis that miR-302b reintroduction would have a major effect on this subtype." (PMID 32806777, 2020). "While reaping the benefits of sustained proliferative signaling requires the cell to be immortal, it is still unclear whether alteration of YY1 alone could give rise to tumor cells with replicative immortality, and thus, further investigation is needed." (PMID 32226547, 2020). "The impacts of O-GlcNAcylation on tumour growth and tumour microenvironment cellular responses seem predominantly mediated by factors, such as YY1, and processes, such as OXPHOS and glycolytic metabolism, that are intimately linked to acetyl-CoA and the regulation of the melatonergic pathway." (PMID 33375613, 2020). "Furthermore, while there are still several crucial concerns need to be solved before its clinical application, these facts also emphasize the prognostic and therapeutic potential of YY1 for anti-tumor therapy." (PMID 32226547, 2020). "Consequently, the YY1-miR-135b suppression of Bmal1 is likely to be an important aspect of how alterations in mitochondrial metabolism occur in the tumour microenvironment." (PMID 35582450, 2020). "Besides, YY1, a ubiquitous protein in normal and tumor tissues, is identified as a potential prognosis biomarker and therapeutic target." (PMID 32280300, 2020). "Together, the ability of YY1 to inhibit apoptosis and its association with CSC maintenance could indicate a broader role for YY1 in tumor biology." (PMID 33102493, 2020). "Notably, YY1 is coupled to invasive properties of malignant tumors, and the gene is in part regulated by PTEN—a tumor suppressor gene recurrently mutated and deleted in FTC." (PMID 33063251, 2020). "It is still unclear in which cases YY1 acts as an oncogene or as a tumor suppressor." (PMID 32899428, 2020). "It is also crucial to reveal whether the role of YY1 as an oncogene or tumor suppressor is related with the cancer types, or even subtypes of cancers, especially when designing anti-tumor therapeutic strategy." (PMID 32226547, 2020). "The YY1 transcription factor significantly increases tumour cell growth and metastasis." (PMID 33375613, 2020). "RACK1 may also be regulated by YY1, indicating wider interactions with factors known to regulate the tumour microenvironment, including the melatonergic pathway." (PMID 33375613, 2020). "We believe that this study extends our knowledge about the regulation of aerobic glycolysis by transcription factor and its derived uPEP, and suggests that MZF1 and YY1 may be potential therapeutic targets for tumor progression." (PMID 32042322, 2020). "Hence, YY1 aids tumor cells in resisting cell death by tipping the apoptosis-anti-apoptosis balance in favor of cell survival, thereby protecting the cells from damage, and by activating autophagy-mediated survival." (PMID 32226547, 2020). "Furthermore, YY1 expression was prominently elevated in cancerous cell lines and tumor tissues than in normal cell line and peritumoral tissues by qRT-PCR analysis." (PMID 32249890, 2020). "In our research, we found that YY1 could suppress tumour progression by directly targeted HOXD3 via ITGA2‐ERK cell signalling." (PMID 32557953, 2020).
tumor (continued). "The multifunctional Yin-Yang 1 (YY1) is involved in the regulation of tumor malignancy of HCC." (PMID 31799179, 2019). "Owing to its central role in tumor progression, YY1 is an attractive drug target." (PMID 31824839, 2019). "YY1 expression analysis in patient derived tumor samples, cancer cell lines, and xenografts." (PMID 31824839, 2019). "It remains to be established whether both RelB and YY1 affect tumor generation or progression, but the later seems to be more likely based on our data." (PMID 31142741, 2019). "Perhaps the cellular context, differential interaction with other pro-tumorigenic vs. tumor suppressive molecules may dictate the behavior of YY1 as a tumor promoter vs. tumor suppressor." (PMID 31824839, 2019). "Finally, we discuss the possibility of therapeutically targeting the YY1 in cancers where it functions as a tumor promoter." (PMID 31824839, 2019). "It is likely that the proteins with which YY1 interacts might determine its function as an activator or repressor of transcription as well as its role as a tumor suppressor or promoter." (PMID 31824839, 2019). "Thus, our study provides evidences regarding the potential of YY1 as a target for lipid metabolism-based anti-tumor therapy." (PMID 31695789, 2019). "YY1 represses p27 expression and thereby promotes tumor formation." (PMID 31824839, 2019). "Negative regulation of LINC00152 and FEN1 by YY1 leads to tumor suppression." (PMID 31824839, 2019). "The inhibition of YY1 sensitizes tumor cells to apoptosis and may be a potential therapeutic target for overcoming immune resistance." (PMID 31533363, 2019). "In vivo, YY1 promoted tumor growth, and angiogenesis formation also relied on VEGFA." (PMID 31799179, 2019). "It is likely, that the opposing roles of YY1 as tumor promoter vs. tumor suppressor depend on the cancer type and its interacting partners by regulating the expression or repression of several genes as well as non-coding RNAs including long non-coding RNAs (lnc) and several microRNAs (miRNAs)." (PMID 31824839, 2019). "Therefore, our study provides evidences regarding the potential of YY1 as a target for anti-tumor therapies based on targeting tumor cell lipid metabolism." (PMID 31695789, 2019). "This raises a question as to whether YY1 functions as a tumor suppressor in the case of HBV mediated liver cancer." (PMID 31824839, 2019). "While upregulation of some lnc-RNAs such as lncRNA-PVT1 by YY1 promotes tumor growth." (PMID 31824839, 2019). "In addition to being O-GlcNacylated, YY1 expression is upregulated in CRC and is linked to tumor proliferation, high grade metastasis and drug resistance." (PMID 31824839, 2019). "In addition to regulating EMT, YY1 overexpression is correlated with tumor progression and drug resistance in prostate cancer." (PMID 31703732, 2019). "Moreover, we confirmed in nude mice that knockdown of YY1 synergistically enhanced cisplatin-induced inhibition of xenograft tumor growth." (PMID 29970878, 2018). "Furthermore, we have shown that nitric oxide (NO) donors, such as DETA/NO, upregulate RKIP by inhibiting the NF-κB/YY1/Snail regulatory circuitry resulting in tumor chemo-immuno-sensitization and inhibition of EMT and metastasis." (PMID 30149591, 2018). "It is possible that these tumor-suppressive effects mainly depend on YY1-induced apoptosis." (PMID 29052509, 2017). "RKIP overexpression may regulate tumor sensitivity to death ligands by inhibiting YY1 and up-regulating death receptors." (PMID 28476134, 2017). "YY1 had also been reported as an oncogene, as its overexpression is observed in various cancers and correlated with poor prognosis, most plausibly through its role in promoting proliferation and colonialization of tumor cells, as well as tumor angiogenesis." (PMID 28903375, 2017).
tumor (continued). "However, as data on its prognostic significance has become available for more human cancers, YY1′s role in tumor progression has become more controversial." (PMID 28412749, 2017). "Together, these data consistently showed that YY2 expression was lower in tumor cells and tissues, and thus might be involved in tumorigenesis in the manner totally different from that of YY1." (PMID 28903375, 2017). "One plausible reason is that YY1 regulates both cell proliferation and apoptosis, and in any given tumor, it may regulate one process more than the other by preferential interaction with available proteins depending on cellular contexts." (PMID 28412749, 2017). "Overexpression of YY1 in tumor tissues exerts different clinical behavior in different tumor types." (PMID 26104682, 2015). "Alternatively, YY1 has also been shown to activate c-myc promoter in tumor cells." (PMID 26104682, 2015). "In addition, treatment of tumor cells with siRNA YY1 resulted in the up regulation of Fas and sensitization to FasL apoptosis." (PMID 25053986, 2014). "In this case, YY1 repressed the tumor suppressing gene and increased the expression of oncogenes." (PMID 25053986, 2014). "We also sought to unravel whether tumor suppressor miR-34 family inhibits gastric carcinogenesis via down-regulating YY1 expression." (PMID 24970812, 2014). "The inhibition of YY1 sensitized the tumor cells to TRAIL apoptosis." (PMID 25053986, 2014). "The increment of tumor sizes in SC-M1 cells by miR-34a knockdown was relieved after YY1 knockdown." (PMID 24970812, 2014). "The miR-34bc-inhibited tumor sizes of SC-M1 cells were restored by YY1 overexpression." (PMID 24970812, 2014). "Therefore, YY1 can act as both a tumor suppressor and an oncogene, depending on tissue context, interaction partners and downstream targets." (PMID 24884523, 2014). "To address whether YY1 knockdown-mediated tumor invasion is dependent on MMP10 activity, we used siRNA experiments to knockdown MMP10 expression in vitro." (PMID 24884523, 2014). "On the other hand, YY1 could suppress tumorigenesis by upregulating tumor suppressor genes such as HLJ1 and BRCA1, and inhibiting c-myc function by direct interaction." (PMID 24884523, 2014). "The multi-faceted protein YY1 and miRNAs could function either oncogenic or tumor-suppressive roles in the tumorigenesis of hematopoietic malignancies and solid tumors." (PMID 24970812, 2014). "The same trend could be observed using a boxplot, which showed that the mean expression level of YY1 in tumors, tumor adjacent normal tissues and normal pancreas was 1.01 ± 1.01, 0.38 ± 0.43 and 0.03 ± 0.01, respectively." (PMID 24884523, 2014). "Several lines of evidence uncovered by the present study and our previous study indicate that YY1 may act as a tumor suppressor in PDAC." (PMID 24884523, 2014). "To identify tumor-suppressive miRNAs modulating gastric carcinogenesis through targeting YY1, we employed widely used software including TargetScan 5.2, PicTar, and miRecords algorithms to search for the putative binding sites of miRNAs in the 3'-UTR of human YY1 mRNA." (PMID 24970812, 2014). "Importantly, we showed that both YY1 and RelA were essential for the colony forming ability of the MM tumor progenitor cells." (PMID 23874387, 2013). "We next investigated the role of YY1 in MM tumor growth by employing xenograft tumor models for human MM in nude mice by subcutaneously injecting KMM1 cells that were infected either with control-ShRNA or ShRNA targeting YY1." (PMID 23874387, 2013). "This prompted us to investigate the function of YY1 in MM tumor survival and growth." (PMID 23874387, 2013).